BACE1 (beta-secretase 1)
Diseases named in the same sentence as BACE1 in open-access papers (continued):
Sharing a sentence is not in itself a finding about the gene and the disease.
amyloid (continued). "Thus, we reasoned that the 5XFAD mouse is an appropriate model for investigating the potential role of eIF2α phosphorylation in BACE1 elevation near amyloid plaques." (PMID 24992504, 2014). "In addition, BACE1 accumulates within presynaptic dystrophies that surround amyloid plaques within the hippocampus and cortex." (PMID 23820808, 2013). "Elevated BACE1 and APP levels in plaque-associated presynaptic dystrophies could increase local peri-plaque Aβ generation and accelerate amyloid plaque growth in AD." (PMID 23820808, 2013). "BACE1 immunoreactivity was colocalized with amyloid plaques in 5XFAD mice." (PMID 24146979, 2013). "However, our results also narrow the possible applications of CSF BACE1 activity due to its selective correlation with brain regional amyloid pathology." (PMID 22272179, 2012). "Finally, although our cross-sectional study demonstrated a correlation between BACE1 activity and in vivo amyloid load, longitudinal studies are necessary to determine the stability or variability of this association over time." (PMID 22272179, 2012). "Moreover, we also found that, in an Alzheimer's mouse model, genetic deletion of TNF receptor (TNFR1) reduces amyloid plaques and amyloid beta peptides (Aβ) production through β-secretase (BACE1) regulation." (PMID 21978728, 2011). "In conclusion, the lack of Aβ generation in the brains of BACE1 deficient mice indicates that therapeutic inhibition of BACE1 should reduce cerebral Aβ levels and amyloid development, an outcome likely to be beneficial for AD." (PMID 18005427, 2007). "Interestingly, Singer and colleagues demonstrated that a partial reduction in BACE1 can improve amyloid neuropathology including the deposition of Aβ, alongside cognitive deficits in APP Tg mice." (PMID 19415126, 2007). "Interestingly, Singer and colleagues used RNA interference (RNAi) to silence BACE1 and demonstrated that a partial reduction in BACE1 can improve amyloid neuropathology including the deposition of Aβ, alongside cognitive deficits in APP Tg mice." (PMID 18005427, 2007). "IL-33 treatment in D-gal–administered mice significantly downregulated BACE1 protein levels in cortex and hippocampus regions, when compared with chronic D-gal–administered mice, suggesting that IL-33 has an inhibitory effect on the progression of amyloid pathology in D-gal–induced aged mice." (PMID 39224568, 2024). "To continue our investigation of the underlying changes leading to epileptiform activity and sleep disturbances, we posed the question of whether there was a difference in amyloid plaque loads in these two AD mouse models following Bace1 deletion or BACE1 inhibition." (PMID 37536983, 2023). "It remains to be established if a partial reduction of BACE1 levels, possibly before the appearance of amyloid pathology, may prevent these detrimental side effects, maintaining the cleavage of substrates other than Aβ and preserving the physiological functions of the enzyme." (PMID 34349120, 2021). "Because 5xFAD is a model that has five mutations and rapidly develops severe amyloid pathology, decreased expression of BACE1 may not be sufficient to reduce Aβ." (PMID 34750393, 2021). "Results of those future studies may allow to draw definitive conclusions on the tolerability and molecular, neurophysiological, and behavioral effects of the BACE-1 inhibitor ER-901356 treatment on the present spectral EEG biomarkers in this popular mouse model of AD-like amyloid neuropathology." (PMID 33260655, 2020). "Therefore, it is intriguing to surmise that mCa2+ overload and the associated oxidative stress may form a maladaptive feed-forward loop with BACE1-mediated amyloidosis." (PMID 31467276, 2019). "Lastly, the increase of both BACE1 and phospho-eIF2α levels in the 5XFAD transgenic mouse model of aggressive amyloid pathology indicates that this animal model could be useful for studying the role of eIF2α phosphorylation in BACE1 elevation and amyloidogenesis in AD." (PMID 24992504, 2014).
amyloid (continued). "An increase in BACE1 level in plaque-associated dystrophic presynaptic terminals, in conjunction with APP accumulation in these neuritic dystrophies, may elevate local peri-plaque Aβ generation and exacerbate the progression of amyloid pathology in AD." (PMID 23820808, 2013). "Pioglitazone inhibits the amyloidogenic pathway, reducing BACE1, PSEN1, Aß42 levels and amyloid plaques, while increasing IDE and Pparg expression in PreDM and T2D models." (PMID 41146261, 2025). "Using microRNA to target the amyloidogenic pathway, the regulatory role of BACE1 and APP has been demonstrated in experimental models of AD utilizing mice that have been manipulated to accumulate amyloid in the brain as their primary pathology." (PMID 39459541, 2024). "It is a reticulon protein, which plays a role in blocking BACE1 access to APP, thereby reducing Aβ production and potentially limiting amyloid plaque formation." (PMID 39535480, 2024). "Approximately 30% downregulation of BACE1 transcript was detected in the hippocampi of the APP/PS1 transgenic mice after four injections of the nanoparticle, and thus led to the decrease of amyloid deposits in the cortex and hippocampus." (PMID 37485250, 2023). "The dark-brown amyloid plaques were observed in the hippocampus CA1 and cortex of AlCl3-induced rats by BACE1 antibody-positive stain (indicated by the red arrows)." (PMID 34884565, 2021). "To investigate the influence of β-secretase activity on the amyloidosis of EAO and isoquercitrin, we measured BACE-1 protein expression in the brain tissue." (PMID 32397362, 2020). "In the amyloidosis process, APP is cleaved by BACE-1 (member of β-secretase) and generates sAPPβ and CTF-β." (PMID 32397362, 2020). "In our study, both EAO and isoquercitrin inhibited protein expression of BACE-1, thereby EAO and isoquercitrin attenuated amyloidosis induced by HFD and Aβ in the brain by down-regulation of β-secretase activity." (PMID 32397362, 2020). "Since ROCK1 inhibition reduced BACE1‐derived β‐CTF, it is concluded that β‐CTF decrease is the key contributor preventing amyloid formation and involved in ameliorating cognitive deficits in Y‐27632‐treated APP/PS1 mice." (PMID 31287605, 2019). "We assessed the amyloidosis changes by YXQN administration, and also detected the proteases involved in the proteolytic process of APP, including ADAM10, BACE1, and PS1, in order to develop the potential Chinese medicine for AD treatment." (PMID 28603494, 2017). "Treatment with NB-360, a potent and brain penetrable BACE-1 inhibitor can completely block the progression of Aβ deposition in the brains of APP transgenic mice, a model for amyloid pathology." (PMID 26336937, 2015). "Because CDK5 phosphorylates tau, APP, and BACE1, a component of the beta-secretase, CDK5 is an important link between amyloid- and tau-pathology." (PMID 23776568, 2013). "BACE-1 is a critical enzyme in the amyloidogenic pathway, responsible for the cleavage of amyloid precursor protein (APP) and the subsequent formation of β-amyloid peptides, which aggregate to form amyloid plaques in AD." (PMID 39598743, 2024). "This has been demonstrated in 5xFAD mice, in which the knockout of BACE1 was able to restore fear memory and reduce amyloid plaque load at 6 months, but showed no significant benefit at 15–18 months." (PMID 36899916, 2023). "As a consequence, BACE1 could lose its capacity to cleave APP, consequently reducing Aβ peptide production and amyloid plaque accumulation." (PMID 35773306, 2022). "This latter possibility, however, was questioned since genetic inhibition of eIF2α phosphorylation was not able to revert the Aβ-dependent BACE1 increase or the amyloid pathology in transgenic AD mice." (PMID 34349120, 2021). "Because amyloid plaques are present at this age point, reduction of BACE1 activity obtained by crossing δE9 with BACE1-KO mice decreased the amyloid burden and restored EE-induced spine formation but did not improve spine stabilization." (PMID 33013348, 2020).
amyloid (continued). "Similarly, BACE1 accumulates in swollen dystrophic neurites in very close proximity to amyloid plaques in the brain of APP transgenic mice and AD patients, suggesting that Aβ toxicity results in BACE1 elevation." (PMID 29391027, 2018). "Finally we discuss the benefit, feasibility and some strategic issues for developing BACE1 inhibitors primarily targeting at CAA, in addition the compounds designated to reduce amyloid plaque lesions explored currently in clinical trials." (PMID 28841840, 2017). "A plausible functional link between reduced amyloidosis and preserved synaptic plasticity is further supported by the improvement of LTP observed in bigenic 5xFAD/BACE1+/− mice, where strong decreases in Aβ levels are comparable to those found in our TgMT5−/− mice." (PMID 26202697, 2016). "This knowledge together with the fact that no amyloid plaques are found in knock-out mice lacking BACE-1, while they seem to be vital and fertile, make inhibition of BACE-1 an interesting approach for targeting AD." (PMID 23585822, 2013). "BACE1 and APP accumulate in presynaptic dystrophies surrounding amyloid plaques, implying a feed-forward mechanism of Aβ generation that may exacerbate AD pathogenesis." (PMID 23820808, 2013). "It has not been studied so far to what extent BACE1 activity in cerebrospinal fluid (CSF) mirrors in vivo amyloid load in AD." (PMID 22272179, 2012). "The early and focal glial activation, in conjunction with upregulated BACE1 mRNA, protein and activity in the presence of its substrate APP, is proposed to represent the earliest sites of amyloid deposition, likely evolving into amyloid plaques." (PMID 16212664, 2005). "In an AD amyloid mouse model lacking BACE1 palmitoylation, reduced BACE1-containing localization within dystrophic neuronal synapses around amyloid plaques led to a significant reduction in local amyloid load, which alleviated cognitive dysfunction in mice." (PMID 40959086, 2025). "Examining the effect of the small molecule on BACE1 and LAMP1 accumulation in dystrophic axons as well as on amyloid plaque pathology could shed more light on the contribution of these pathways to AD pathogenesis and the therapeutic potential of manipulating AP-4-dependent pathways in AD treatment." (PMID 39632089, 2024). "We crossed the Bace1fl/fl;Olig2-Cre model with heterozygous AppNL−G−F/wt knock-in AD mice to generate AD mice lacking oligodendrocyte Bace1 (Bace1fl/fl;Olig2-Cre; AppNL−G−F/wt) and examined amyloid plaque number and insoluble Aβ levels and gliosis in these animals." (PMID 39548583, 2024). "Our study results show that TBN could decrease the levels of APP, BACE1 and PS1, and increase the levels of NEP, indicated that TBN prevents the amyloid plaque formation and enhances amyloid degradation, which account for the reduction levels of Aβ production and deposition in 3×Tg-AD mouse model." (PMID 36950017, 2023). "Although neurons account for most BACE1-mediated Aβ synthesis in AD, it has been demonstrated that inflammatory mediators, such as IFN-γ, TNF-α, and IL-1β, induce the expression of BACE1 and the release of Aβ in astrocytes, suggesting that these cells also contribute to the amyloidosis in AD." (PMID 30249283, 2018). "The amounts of BACE1 labelled dystrophic neurites do not always match to the extent of amyloidosis anatomically and densitometrically in postmortem human brains, with Aß deposition appeared much denser relative to neuritic profiles especially among the cases with advanced AD pathologies." (PMID 28841840, 2017). "Thus, we endeavored to find an alternative substrate-based inhibitor for BACE1 that does not lead to aberrant amyloidosis." (PMID 26091071, 2015). "Thus, we can conclude that eIF2α phosphorylation does not have a role in Aβ-associated BACE1 and APP elevation, or in amyloid pathology, at least in primary neurons and 5XFAD mice." (PMID 24992504, 2014).
amyloid (continued). "It should be noted that BACE1 levels were significantly increased in the brains of D257A; APP/Ld and APP/Ld compared to D257A and wild-type mice, consistent with our previous work showing that BACE1 levels are elevated by amyloid pathology in human AD and APP transgenic mouse brains." (PMID 24885175, 2014). "Thus, our data implicate that CSF BACE1 activity reflects AD pathology in particular brain regions, whereas [11C]PIB tracer uptake may map the entire cerebral amyloid load." (PMID 22272179, 2012). "5XFAD;BACE1−/− mice, which overexpress APP and PS1 transgenes but do not generate Aβ, allowed us to determine if changes in ER stress occurred, and if so, whether they were caused by amyloid pathology or by prolonged overexpression of APP and PS1." (PMID 30315100, 2018). "Similar to the 5XFAD brain, BACE1 and synaptophysin displayed significant co-localization surrounding amyloid plaques, while MAP2 did not overlap with BACE1 in the AD brain." (PMID 23820808, 2013).
neuroblastoma (76 papers, 2010 to 2026). Neuroblastoma (NB) is the most common solid, extracranial childhood tumor. "Wildtype and mutated Navβ2 were transfected into B104 rat neuroblastoma cells stably overexpressing BACE1." (PMID 21182789, 2010). "Finally, wildtype and mutated Navβ2 were expressed along BACE1 in B104 rat neuroblastoma cells." (PMID 21182789, 2010). "It inhibits Aβ aggregation by influencing BACE1 activity and promotes autophagy for clearing harmful proteins, significantly decreasing cytotoxicity in neuroblastoma cells and lowering oxidative stress levels." (PMID 39684911, 2024). "In this study, we evaluated the effects of Ramalin and its chloride derivatives on the regulation of BACE-1 expression using the murine and human neuroblastoma cell lines N2a and SH-SY5Y, respectively." (PMID 39125105, 2024). "A previous study using human and mouse neuroblastoma cell culture suggests that inhibition of GSK-3β by AR-A014418 decreases APP cleavage by BACE1, reducing the production of Aβ peptides." (PMID 38574297, 2024). "MiR-124 levels are downregulated in sporadic AD brain tissues, and miR-124 can inhibit BACE1 expression in human neuroblastoma cells and AD mouse models." (PMID 38003448, 2023). "MiR-15b modulates BACE1 expression in human neuroblastoma cells, and its levels are decreased in sporadic AD brain tissues." (PMID 38003448, 2023). "MiR-135a inhibits BACE1 expression in human neuroblastoma cells and primary mouse hippocampal neurons and its levels are reduced in the serum of AD patients." (PMID 38003448, 2023). "HuD stabilize the APP mRNA, BACE1 mRNA, and BACE1-AS lncRNA in neuroblastoma cells, leading to Aβ accumulation." (PMID 36552825, 2022). "For example, in vitro caffeine decreased Aβ level and Aβ1-42 deposition, and reduced BACE-1 activity in human neuroblastoma SH-SY5Y cells, and inhibited oligomerization of Aβ in N2a/APP cells." (PMID 33562156, 2021). "To elucidate the function of miR-1273g-3p in neuronal cells, we analyzed the changes of mitochondrial function and BACE1 expression using neuroblastoma cell line SH-SY5Y." (PMID 34685681, 2021). "Oxidative stress has been shown to activate BACE1 (including gene expression) in neuroblastoma cells and NT2 neurons and that this is partly mediated by γ-secretase." (PMID 34679674, 2021). "Studies conducted in primary mouse cortical neurons (MCN) and neuroblastoma Neuro2a (N2a) cells show that miRNA-125b binds to the BACE1 protein with an inhibitory effect on its expression levels and mitigates Aβ-induced neurotoxicity." (PMID 33504764, 2021). "Overexpression of wild type or mutant APP caused mitochondrial fragmentation in M17 neuroblastoma cells and primary neurons, which was blocked by beta-APP cleaving enzyme (BACE1) inhibitor, suggesting that Aβ induced this effect." (PMID 32471464, 2020). "Tolfenamic acid inhibited the transcription factor Sp1, which reduced the transcription of APP and BACE1 in Pb-exposed human neuroblastoma SH-SY5Y cells and decreased Aβ accumulation in APP transgenic mice." (PMID 32517647, 2020). "Human neuroblastoma cells were treated with 0.25 μM Aβ1-42 oligomers for 24 h, and BACE1 mRNA showed a significant transcriptional increase (p < 0.05)." (PMID 33014268, 2020). "Our study reveals a consistent inhibitory effect of miR-15b on the modulation of BACE1 expression in human neuroblastoma cell line and further demonstrates the role of miR-15b in the reduction in APP and Aβ levels in a human AD cell model." (PMID 29961672, 2018). "In human, SK-N-MC neuroblastoma cells ethanol upregulated BACE1 expression and Aβ production, as well as increased reactive oxygen species (ROS) production, cyclooxygenase-2 (COX-2) expression and PGE2 production." (PMID 29759078, 2018). "miR-98-5p is up-regulated in AD patients and promotes BACE1 expression and Aβ level in neuroblastoma cell line." (PMID 29961672, 2018).